EIF4E (eukaryotic translation initiation factor 4E)
Diseases named in the same sentence as EIF4E in open-access papers (continued):
Sharing a sentence is not in itself a finding about the gene and the disease.
Obesity (3 papers, 2018 to 2023). Accumulation of substantial excess body fat. "Recent studies have shown that eIF4E can inhibit obesity and fatty liver caused by high-fat food." (PMID 37601696, 2023). "This also supports the statement that there is a connection between eIF4E, obesity and cancer development." (PMID 37601696, 2023). "The major cap-binding protein eIF4E was shown as a regulator of lipid homeostasis and diet-induced obesity." (PMID 36014915, 2022). "Recently, the role of a translation factor—eukaryotic translation initiation factor 4E (eIF4E)—was assessed in the obesity pathogenesis." (PMID 36014915, 2022). "In conclusion, the translation control of eIF4E may be the driving factor of weight gain induced by high-fat diet and eIF4E can be used as a pharmacological target for obesity treatment." (PMID 37601696, 2023). "In line with this evidence, eIF4E, a molecule that is part of the eIF4F complex, which mediates translational control and is strongly associated with tumorigenesis, is also affected by HFD-induced obesity thereby supporting the link between obesity and HCC." (PMID 30224299, 2018). "Therefore, the relationship among obesity, canceration and eIF4E may become a new direction for the study of eIF4E." (PMID 37601696, 2023).
Breast invasive carcinoma (2 papers, 2006 to 2021). "Further subgroup analysis of multiple clinicopathological features of TCGA-Breast invasive carcinoma samples in the UALCAN database consistently showed an increase in the transcript level of eIF4E." (PMID 34876062, 2021). "In conclusion, the results of this study provide evidence that the immunohistochemical level of eIF4E expression is markedly upregulated in high-grade invasive breast cancer tissues." (PMID 17010208, 2006).
Burkitt lymphoma (2 papers, 2014 to 2021). A rare form of malignant mature B-cell non-Hodgkin lymphoma. "Another study showed that lncRNA MCM3AP-AS1 enhances the expression of eIF4E by acting as a sponge for miR15a, which supresses eIF4E expression and contributes to doxorubicin resistance in Burkitt lymphoma cells through MCM3AP-AS1/miR-15a/eIF4E axis." (PMID 33672592, 2021). "In accord, a search of the Oncomine database revealed frequent overexpression of eIF4E mRNA in Burkitt’s Lymphoma, a cancer driven by Myc." (PMID 24586420, 2014).
colorectal adenocarcinoma (2 papers, 2016 to 2021). The most common type of colorectal carcinoma. "Evidence suggests that the high abundance of the eIF4E protein is strongly related to the histological type of lesion, with colorectal adenocarcinomas showing the highest eIF4E expression." (PMID 33382175, 2021).
dementia (2 papers, 2022 to 2023). Loss of intellectual abilities interfering with an individual's social and occupational functions. "These loci are associated with several dementia-related genes, including PON1, AP2A2, MAGI2, POT1, ITGAX, PACSIN1, SLC2A8, and EIF4E." (PMID 35299244, 2022).
epilepsy (2 papers, 2023 to 2025). A brain disorder characterized by episodes of abnormally increased neuronal discharge resulting in transient episodes of sensory or motor neurological dysfunction, or psychic dysfunction. "We found that genes of the mTOR pathway (RPS6, RHEB, EIF4E) were highly expressed in the PY2 pyramidal neurons, consistent with the activation of the mTOR pathway in histopathological neurons in the epileptic focus of drug-resistant epilepsy." (PMID 40026248, 2025).
HIV-1 infection (2 papers, 2012). The type species of lentivirus and the etiologic agent of acquired immunodeficiency syndrome (AIDS). "Using multiple approaches, we demonstrated that the host cell translation is suppressed during acute HIV-1 infection, an effect associated with reduced levels of phosphorylated eIF4E and 4E-BP1." (PMID 22457629, 2012). "Moreover, the perturbation of eIF4E, a critical regulator of other transcription or translation factors including Cyclin D1, and Pim-1, may also result in an inhibition of HIV-1 infection." (PMID 22808186, 2012).
liposarcoma (2 papers, 2008 to 2016). A usually painless malignant tumor that arises from adipose tissue. "Another angiogenesis-targeting therapeutic, 4EGI-1, which targets the oncoprotein eIF4E, significantly decreased angiogenic ligand expression by myxoid liposarcoma cells and reduced tumor cell growth." (PMID 27822137, 2016). "The loss of VEGF ligands and receptor expression after pharmaceutical inhibition with 4EGI-1 confirmed that eIF4E promotes some angiogenic properties of myxoid liposarcoma cell lines." (PMID 27822137, 2016). "Together, these findings indicate that the 4EGI-1 inhibitor was highly specific for eIF4E, with an increased sensitivity of the myxoid liposarcoma cells to eIF4E inhibition." (PMID 27822137, 2016). "Reporter assays showed FUS-DDIT3 is involved in the upregulation of eIF4E in liposarcomas and that both domains of the fusion protein are required for affecting eIF4E expression." (PMID 18596980, 2008). "Interestingly, we found high levels of eIF4E and eIF2α in liposarcomas, two translation initiation factors involved in controlling the ratio of C/EBP isoforms." (PMID 18596980, 2008). "When U2OS cells were co-transfected with the reported vector along with the FUS-DDIT3 expression vector, there was a specific increae of the CAT activity compared to the activity with the empty vector, demonstrating that FUS-DDIT3 is involved in the upregulation of eIF4E in liposarcomas." (PMID 18596980, 2008). "Analysis by western-blot of protein lysates showed a dramatic overexpression of both eIF4E and eIF2 in liposarcomas arisen both in FUS-DDIT3 mice and human liposarcomas cell lines FUS-DDIT3 positives, explaining the shift towards the truncated p30 isoform of C/EBPα in liposarcomas." (PMID 18596980, 2008). "Thus, we next studied the expression level of eIF2α and eIF4E in FUS-DDIT3-liposarcomas." (PMID 18596980, 2008). "Moreover, eIF4E was also strongly upregulated in normal adipose tissue of FUS-DDIT3 transgenic mice, suggesting that overexpression of eIF4E may be a primary event in the initiation of liposarcomas." (PMID 18596980, 2008). "In this sense, eIF4E was also strongly upregulated in normal adipose tissue of FUS-DDIT3 transgenic mice, suggesting that overexpression of eIF4E may be one of the primary events in the initiation of liposarcomas." (PMID 18596980, 2008). "Moreover, FUS-DDIT3 is able to transactivate the eIF4E promoter suggesting that FUS-DDIT3 is able to interfere with the translational initiation machinery and disrupt the normal adipocyte differentiation program of adipocyte progenitor cells in liposarcomas." (PMID 18596980, 2008). "Moreover, eIF4E was also strongly upregulated in normal WAT of FUS-DDIT3 transgenic mice, suggesting that overexpression of eIF4E may be one of the first events in the initiation of liposarcomas." (PMID 18596980, 2008).
malignant glioma (2 papers, 2014 to 2020). A grade III or grade IV glioma arising from the central nervous system. "Therefore, the purpose of this study was to investigate the effect of apoptosis induced by borneol in human malignant glioma primary cells, and the effect and relation of borneol on regulation of the mTORC1/eIF4E/HIF-1a signaling pathway." (PMID 32626528, 2020). "In order to clarify the exact mechanism of borneol induced apoptosis in malignant glioma, this study further evaluated the effect of Borneol on HIF-1α, mTORC1, eIF4E expression." (PMID 32626528, 2020). "Furthermore, IMPDH was not included in the present study as it was reported that ribavirin inhibits leukemic cell proliferation through multiple signaling pathways, therefore, ribavirin may act on malignant glioma cells via mechanisms that do not involve eIF4E or IMPDH." (PMID 25364409, 2014).
mantle cell lymphoma (2 papers, 2015 to 2021). Mantle cell lymphoma is a rare form of malignant non-Hodgkin lymphoma affecting B lymphocytes in the lymph nodes in a region called the ``mantle zone''. "lncRNAs SNHG1 and SNGH4 are capable of binding to eIF4E and dysregulate the function of eIF4E in mantle cell lymphoma cells." (PMID 33672592, 2021). "For example, vorinostat suppresses cyclin D1 in mantle cell lymphoma cells by blocking the translation of cyclin D1 via inhibiting the phosphatidylinositol 3-kinase (PI3K)/Akt/mTOR/eIF4E-BP pathway most likely by PI3K inhibition." (PMID 26681199, 2015).
medulloblastoma (2 papers, 2014 to 2021). A malignant, invasive embryonal neoplasm arising from the cerebellum. "In initial studies, we sought to examine the effects of different mTOR inhibitors on the phosphorylation/activation of eIF4E in human medulloblastoma cells." (PMID 25193863, 2014). "Here, we investigated the mechanisms by which rapamycin increases eIF4E phosphorylation in Daoy medulloblastoma cells and the relevance of this phosphorylation in counter-acting its antineoplastic effects." (PMID 25193863, 2014). "Treatment of Daoy medulloblastoma cells with rapamycin induced phosphorylation of eIF4E on Ser-209, suggesting activation of a feedback loop during mTORC1 inhibition in these cells." (PMID 25193863, 2014). "This eIF4E phosphorylation is Mnk2- mediated, but Mnk1-independent, and acts as a survival mechanism for medulloblastoma cells." (PMID 25193863, 2014). "To define whether rapamycin-induced increase in eIF4E phosphorylation is mediated by Mnk1 or Mnk2, we knocked down Mnk1 or Mnk2 in Daoy medulloblastoma cells, and examined the effects of such knockdown on rapamycin-inducible eIF4E phosphorylation." (PMID 25193863, 2014). "To define which components of the MAPK pathway are required for rapamycin-dependent eIF4E phosphorylation in medulloblastoma cells, we treated Daoy cells with a panel of protein kinase inhibitors to disrupt MAPK signaling and investigated induction of eIF4E phosphorylation under these conditions." (PMID 25193863, 2014). "In the present study, we sought to determine whether eIF4E phosphorylation accounts for resistance to mTORC1 inhibition in medulloblastoma cells and, if so, to investigate the mechanisms of cross-talk between the mTOR and Mnk pathways in medulloblastoma cells." (PMID 25193863, 2014). "This systematic review highlights the mechanisms of resistance of mTOR inhibitors in medulloblastoma and includes IDO1, T cells, Mnk2, and eIF4E, as they prolong malignant cell survival." (PMID 35008889, 2021). "We provide evidence that mTORC1 inhibition by rapamycin results in engagement of a negative feedback regulatory loop in malignant medulloblastoma cells, involving phosphorylation of the eukaryotic translation-initiation factor eIF4E." (PMID 25193863, 2014). "Our findings suggest a similar mechanism in medulloblastoma cells, as demonstrated by experiments demonstrating that Mnk2, but not Mnk1, is essential for rapamycin-induced eIF4E phosphorylation in Daoy cells." (PMID 25193863, 2014).
pancreatic ductal adenocarcinoma (2 papers, 2017 to 2025). An infiltrating adenocarcinoma that arises from the epithelial cells of the pancreas. "The correlation of p-eIF4E with disease grade, disease early-onset, and poor prognosis in pancreatic ductal adenocarcinoma depends on MNK2 phosphorylation of eIF4E." (PMID 28878291, 2017).
prostate tumor (2 papers, 2020 to 2023). "4EASO can effectively down-regulate the expression of eIF4E protein in breast and prostate tumor xenografts, significantly inhibits tumor growth by binding to eIF4E mRNA, triggering RNA degradation mediated by RNA enzyme H." (PMID 37601696, 2023). "MNK/eIF4E pathway involvement in prostate tumor progression has been also reported in vitro and in animal models." (PMID 32340135, 2020).
type 2 diabetes (2 papers, 2020 to 2021). "Higher levels of circulating factor 4E binding proteins E and A (eIF4E and eIF4A) are associated with lowered risk of type-2 diabetes." (PMID 33505701, 2021). "We investigated whether the risk of type 2 diabetes varied with genetically predicted EIF-4E, EIF-4A, EIF-4G, EIF4EBP, and RP-S6K circulating levels using Mendelian Randomization." (PMID 32978410, 2020). "EIF-4E and EIF-4A may be targeted for intervention by repurposing existing therapeutics to reduce the risk of type 2 diabetes." (PMID 32978410, 2020). "This unbiased MR approach found that EIF-4E and EIF-4A, which are essential for 5′-cap-dependent mRNA translation, could have a causal protective association with type 2 diabetes." (PMID 32978410, 2020). "In this study, we investigated whether the risk of type 2 diabetes varied with EIF4EBP2, EIF-4E, EIF-4G, EIF-4A, and RP-S6K levels using the Mendelian Randomization approach." (PMID 32978410, 2020). "EIF-4E and EIF-4A circulating levels, critical regulators of gene translation and protein functions, may be targets for intervention by repurposing existing therapeutics to reduce the risk of type 2 diabetes." (PMID 32978410, 2020). "Thus, we propose that EIF-4E and EIF-4A translation initiation proteins may have a protective effect on type 2 diabetes that is possibly mediated via NLPR12 inflammasome, which regulates the gut microbiome." (PMID 32978410, 2020).
acute promyelocytic leukemia (1 paper, 2022). An aggressive form of acute myeloid leukemia (AML), characterized by arrest of leukocyte differentiation at the promyelocyte stage, due to a specific chromosomal translocation t(15;17) in myeloid cells. "Additionally, the same effects of ATRA and ATPR on eIF4E, eIF4G, and eIF4A were observed in another AML cell line NB4, originating from acute promyelocytic leukemia (APL) patient with high-sensitive to ATRA-induced cell differentiation." (PMID 36365147, 2022).
adenoma (1 paper, 2020). A neoplasm arising from the epithelium. "We also found that p-4E, not total eIF4E, is highly elevated in human adenomas, consistent with highly elevated Myc protein in these precursor lesions and modestly elevated mRNA." (PMID 33135632, 2020).
alopecia (1 paper, 2013). Hair loss usually from the scalp. "Our results demonstrate that transient inhibition of eIF4E protects against cyclophosphamide-induced alopecia at the organismal level." (PMID 24219888, 2013). "Suppression eIF4E in cells of the hair follicles provided profound protection against chemotherapy-induced alopecia." (PMID 24219888, 2013).
bladder tumors (1 paper, 2021). "Phosphorylation of eIF4E at S209 is dispensable for normal urothelial homeostasis and necessary for carcinogen-induced bladder tumor initiation." (PMID 34032633, 2021). "Through a candidate gene analysis of key translation regulators, we determine that phosphorylation of the oncogene eukaryotic translation initiation factor 4E (eIF4E) is significantly upregulated in the context of bladder tumor formation." (PMID 34032633, 2021). "Moreover, we found that eIF4E phosphorylation levels dictate the ability of bladder tumors to respond to the clinical-grade MNK1 and MNK2 inhibitor eFT508." (PMID 34032633, 2021).
central nervous system lymphoma (1 paper, 2014). "Inhibition of eIF4E phosphorylation reduces cell growth and proliferation in primary central nervous system lymphoma cells." (PMID 24551240, 2014).
chordoma (1 paper, 2009). Chordomas are rare malignant tumors arising from embryonic remnants of the notochord in axial skeleton. "Chordomas were positive for p-AKT (92%), p-TSC2 (96%), p-mTOR (27%), total mTOR (75%), p-p70S6K (62%), p-RPS6 (22%), p-4E-BP1 (96%) and eIF-4E (98%)." (PMID 19401700, 2009). "Nevertheless, our findings provide an evidence base for treating selected chordomas with mTOR, AKT inhibitors and antisense molecules to the attractive cancer target, eIF-4E." (PMID 19401700, 2009). "More than 90% of the chordomas expressed p-AKT (Ser243), p-TSC2 (Thr1462), p-4E-BP1 (Thr70) and eIF-4E as assessed by IHC." (PMID 19401700, 2009). "Of the 13 (27%) immunoreactive chordomas for p-mTOR, 12 were immunoreactive for total mTOR protein and showed two copies of the mTOR by FISH, where data were available, and all showed phosphorylation of 4E-BP1 and expressed eIF-4E." (PMID 19401700, 2009).
Cirrhosis (1 paper, 2012). A chronic disorder of the liver in which liver tissue becomes scarred and is partially replaced by regenerative nodules and fibrotic tissue resulting in loss of liver function. "Overall, critical genes encoding for positive cell cycle progression factors (CCND1, CDK1, CDK2, E2F3, EIF4E, and MDM2) were found significantly up-regulated in HCV-cirrhosis with HCC." (PMID 22792259, 2012).
colorectal tumors (1 paper, 2022). "Furthermore, FGFR3 and eIF4E have been found to be actively expressed in a variety of malignancies, including lung, prostate, and colorectal tumors, which cause disease." (PMID 36364261, 2022).
COVID-19 (1 paper, 2024). A disease caused by infection with severe acute respiratory syndrome coronavirus 2. "Studies have also shown that compared with controls, the lung tissue of patients who died of COVID-19 had upregulated expression of proteins such as NPC1/2, CEACAM1, CTSL, EIF4E, and PABPN1, which involve virus-binding receptors, proteases, host mRNA degradation, and translation cessation." (PMID 38752128, 2024).
diffuse astrocytoma (1 paper, 2016). A low-grade (WHO grade II) astrocytic neoplasm. "Hscore (median values and confidence interval) for p4E‐BP1, 4E‐BP1, peIF4E, eIF4E, EGFR, pS6, and pMAPK in gliosis cases, grade II diffuse astrocytomas, AA, and GBM." (PMID 27440383, 2016).
fibrosarcoma (1 paper, 2021). A malignant mesenchymal fibroblastic neoplasm affecting the soft tissue and bone. "eIF4E is considered a central player in carcinogenesis as high levels of the protein induce oncogenic transformation in mouse fibroblasts, while antisense-mediated decrease in eIF4E reverses the aggressive proliferative phenotype of Ras-transformed fibrosarcomas." (PMID 35048066, 2021).
gallbladder cancer (1 paper, 2023). "In addition, it has been shown that the upregulation of eukaryotic translation initiation factor 4E enhances cell proliferation both in vitro and in vivo and is linked to an unsatisfactory prognosis in cases of gallbladder cancer." (PMID 36998056, 2023).
Gliosis (1 paper, 2016). Gliosis is the focal proliferation of glial cells in the central nervous system. "Levels of p4E‐BP1, 4E‐BP1, peIF4E, eIF4E, and cyclin D1 and the Ki67 proliferative index were significantly lower in gliosis than in neoplasm in the whole group (P = 0.004 for cyclin D1, P < 0.001 for the other proteins)." (PMID 27440383, 2016).
HCMV infection (1 paper, 2016). "HCMV infection also activates the MNK kinases, which phosphorylate eIF4E." (PMID 27089357, 2016).
heart failure (1 paper, 2020). Inability of the heart to pump blood at an adequate rate to meet tissue metabolic requirements. "In fact, when both mTOR and 4E-BP1 are deleted, heart failure phenotypes are improved due to unrestricted availability of eIF4E." (PMID 32722591, 2020).
hyperglycaemia (1 paper, 2017). "Genetic reconstitution experiments demonstrate that hyperglycaemia in βraKO mice was partially rescued by gain of 4E-BP2/eiF4E, S6K or both." (PMID 28699639, 2017). "Surprisingly, restoration of S6K together with 4E-BP2/eIF4E signalling was sufficient to normalize β-cell mass but not hyperglycaemia." (PMID 28699639, 2017). "Assessment of glucose levels in these genetic models showed that hyperglycaemia measured by random fed blood glucose was partially rescued by restoration of 4EBP2/eIF4E or S6k signalling in βraKO mice, but not by 4EBP1/eIF4E." (PMID 28699639, 2017).